RN7SKP35 (RN7SK pseudogene 35)
Gene: Miscellaneous RNA gene on chromosome 4 (151,576,766 to 151,576,916, forward strand). Ensembl gene ENSG00000253019.
Homologues: Orthologues: chimpanzee 7SK (100% identical), guinea pig 7SK (54% identical). Paralogues in human: RN7SKP62 (70% identical), RN7SKP185 (66% identical), 7SK (64% identical), RN7SKP160 (64% identical), RN7SKP178 (64% identical), RN7SKP55 (62% identical), RN7SKP121 (62% identical), RN7SKP159 (62% identical), RN7SKP191 (62% identical), RN7SKP210 (62% identical), RN7SKP30 (62% identical), RN7SKP48 (62% identical), and 284 more.